CD4 (CD4 molecule)
Diseases named in the same sentence as CD4 in open-access papers (continued):
Sharing a sentence is not in itself a finding about the gene and the disease.
liver fibrosis (continued). "Baseline CD4+ lymphocyte count, HCV and HIV viral loads, previous treatment and liver fibrosis were not predictors of SVR, as opposed to data that have been reported from large multi-center trials or single center studies." (PMID 23874441, 2013). "However, the difference between CD4+ and CD8+ lymphocytes were not significant in the liver fibrosis group and the nonfibrosis group." (PMID 38270318, 2024). "In this study, the majority of patients was no/mild liver fibrosis by APRI score (68%) and GT1 was predominant genotype (66%), as well as the HIV status was good regarding high CD4 count and low HIV viral load, which may explain the high SVR rate." (PMID 36852142, 2023). "Indeed, patients with significant liver fibrosis and without NAFLD had a lower CD4 cell count and a higher proportion of exposure to didanosine, while metabolic comorbidities and high BMI were less frequent." (PMID 35207770, 2022). "On the contrary, liver fibrosis stage was not correlated with BMI, gender, sexual orientation or HIV-relevant disease markers (CD4 count, CD4/CD8 ratio, HIV duration, duration of ART and ART-free duration of HIV infection, months of low CD4 count and viral load of more than 50 cop/ml)." (PMID 32252653, 2020). "Thus, although Egr2 might be a target for liver fibrosis in MASH, Egr2 should be targeted selectively in monocytes and macrophages in order not to inhibit protective responses by LAG3+CD4+CD25- regulatory T cells." (PMID 38831027, 2024). "Moreover no HIV-related parameters, other than CD4/CD8 ratio, were correlated with liver fibrosis." (PMID 32252653, 2020).
cryptococcosis (168 papers, 2004 to 2026). An acute or chronic, localized or disseminated infection by Cryptococcus neoformans. "For those patients with a CD4 count less than 200 cells/μl (the group most at risk for cryptococcosis), the sensitivity increased to 98%." (PMID 40198673, 2025). "Profound CD4 T cell deficiency is associated with the development of cryptococcosis in HIV-infected individuals." (PMID 39982066, 2025). "In individuals with advanced HIV disease and CD4 ≤ 100/μL in 2014, cryptococcal infection accounted for 15% of all causes of death; by 2020, it constituted 19% of mortality in those with CD4 < 200 cells/μL." (PMID 39221366, 2024). "In contrast, consistent with their paramount role in host defenses against cryptococcosis, protection endowed by the cda1∆2∆3∆ vaccine was completely lost in mice congenitally deficient in CD4+ T cells." (PMID 38980038, 2024). "Deficiency in Batf3 cDC1 led to diminished CD4 accumulation and decreased IFNγ production across multiple organs, supporting that cDC1s are a major driver of potent Th1 responses during cryptococcal infection." (PMID 38349130, 2024). "The use of pomalidomide causes decreased activation of CD4 T-cells, leading to increased susceptibility towards cryptococcal infection due to the altered cell-mediated immune response." (PMID 39803017, 2024). "The CD4+ T lymphocyte subsets Th1 and (to a lesser extent) Th17 have been associated with protective responses to cryptococcal infection." (PMID 36732332, 2023). "An additional challenge to translate our findings to humans is the impairments in CD4+ T cell function present in most individuals at risk for cryptococcosis." (PMID 35089095, 2022). "In this study, we provide evidence for the underlying immune mechanism of host vaccine protection by C. neoformans Δsgl1 during the predisposing condition of cryptococcosis (CD4+ T cell deficiency)." (PMID 36229573, 2022). "In the present study, we validate three different models of successful vaccination strategies against cryptococcosis using heat-killed (HK) C. neoformans Δsgl1 in condition of CD4+ T cell deficiency." (PMID 35615354, 2022). "Our results suggest that HK Δsgl1 represents a clinically relevant, efficacious vaccine that confers robust host protection in three models of vaccination against cryptococcosis even during CD4-deficiency." (PMID 35615354, 2022). "CMI by CD4+TH1 cells is the primary host defense response against cryptococcosis, which is evidenced clinically by the high susceptibility of individuals with reduced CMI to C. neoformans infections." (PMID 35835754, 2022). "Among HIV‐infected adults, CD4 T‐cell count < 100 cell/μL is one of the risk factors for cryptococcosis." (PMID 32472727, 2020). "In this study, CD4 T‐cell frequency was low at onset of HIV‐associated cryptococcosis among individuals who later developed cryptococcal IRIS." (PMID 32472727, 2020). "HIV, which is characterized by a decline in CD4+ T cells, is one of the major causes of cryptococcosis." (PMID 32349734, 2020). "Recent studies have shown that novel acquired immunodeficiencies, such as idiopathic CD4 lymphocytopenia and anti-granulocyte macrophage colony-stimulating factor (anti-GM-CSF), are strongly associated with cryptococcosis." (PMID 31437259, 2019). "Susceptibility to cryptococcosis is tightly linked to host immunity where CD4+ T cells play an essential role in defense." (PMID 29317510, 2018). "Immune responses are critically required for the prevention of cryptococcosis, and patients with impaired immunity and low CD4+ T cell numbers are at high risk of developing these deadly infections." (PMID 29317510, 2018). "CD4 + T-lymphocyte deficiency is one of a main predisposing factors of cryptococcosis, whereby a CD4+ T-cell count below 100 cells/μl and detectable serum cryptococcal antigen portend high risk for HIV-associated cryptococcosis." (PMID 29237413, 2017).
cryptococcosis (continued). "Idiopathic CD4+ T lymphocytopenia has also been reported to be an important predisposing factor for cryptococcosis." (PMID 28035481, 2017). "Rare causes of lymphadenopathy in our study included one case of Cryptococcosis (microbiologically confirmed) in an HIV positive male patient who had profound immunosuppression (CD4 count of 8 cells/ul)." (PMID 26091519, 2015). "It has been known that depletion of CD4 T cells is the most critical predisposing factor to cryptococcosis in HIV infected patients." (PMID 26252005, 2015). "It has been shown that IL-5 produced by CD4 T cells is required for eosinophilia in the context of cryptococcal infection and IL-5 overexpressing mice are highly susceptible to C. neoformans infection." (PMID 26252005, 2015). "Low CD4+ cell counts predispose these patients to cryptococcal infection because of dysfunctional immune systems." (PMID 22417404, 2012). "Cryptococcal infection is a frequent cause of mortality in Cambodian HIV-infected patients with CD4+ count ≤100 cells/μl." (PMID 21085478, 2010). "HIV/AIDS immunocompromised populations deficient in CD4+ T cells are highly susceptible to cryptococcosis disease and thus emphasize the importance of T cell-mediated immunity in the context of the host response against cryptococcal infection." (PMID 41313167, 2026). "As the patient population susceptible to cryptococcosis often includes individuals with compromised adaptive immunity, particularly CD4+ T cell deficiencies, we next assessed whether T and B cells contribute to the host response to chs3Δ." (PMID 40666971, 2025). "As deficiencies in CD4+ T cell function are the major risk factor for cryptococcosis, an unanswered question is whether T cell vaccines will be protective in at risk humans." (PMID 38976694, 2024). "We hypothesize that CD4+ T lymphocytopenia in the patients in this case series could increase the risk of cryptococcosis after SARS-CoV-2 infection." (PMID 36977183, 2023). "Therefore, new modeling approaches should be developed to easily predict cryptococcal infections and their associated mortality, considering other factors such as the CD4 T-cell count-altered mental status, and intracranial pressure, or CrAg serum titers." (PMID 37623607, 2023). "However, populations at risk for cryptococcosis generally are only partially deficient in CD4+ T cell function." (PMID 36732332, 2023). "Given the clinical significance of T cell deficiency to the susceptibility to cryptococcosis in patients, it is also critical to know whether host protection can be established following HK-fbp1 vaccination in both CD4+ and CD8+ T cell-deficient hosts." (PMID 36719231, 2023). "More recently, DCs pulsed with an acapsular C. gattii were used in a vaccine against C. gattii and were able to induce cytokine-producing CD4+ T cells and multinucleated giant cells, which were associated with protection against pulmonary cryptococcosis in an experimental model." (PMID 37367569, 2023). "It is currently believed that HIV–positive persons especially those with advanced condition or CD4 lymphocyte ≤100 cells/μl are more susceptible to cryptococcosis complications-derived deaths than tuberculosis, and the infection remains neglected in research, funding, and policy." (PMID 36006867, 2022). "However, the true standout characteristic for a clinically relevant vaccine formulation is the ability to induce protection in a model most associated with a disease, which is CD4-deficiency for cryptococcosis." (PMID 35615354, 2022). "This means that the vulnerable, low CD4 patients may be put at risk if they have TB or cryptococcal infection that may preferentially require treatment initiation before starting ART." (PMID 35136596, 2022).
cryptococcosis (continued). "We previously reported that administration of Cryptococcus neoformans Δsgl1 mutant vaccine, accumulating sterylglucosides (SGs) and having normal capsule (GXM), protects mice from a subsequent infection even during CD4+ T cells deficiency, a condition commonly associated with cryptococcosis." (PMID 36229573, 2022). "As individuals with CD4+ T cell deficiencies are at increased risk for cryptococcal infections, the potential clinical impact of these observations is unknown." (PMID 36248898, 2022). "We previously reported that a C. neoformans mutant (Δsgl1) accumulating sterylglucosides (SGs) is avirulent and provides complete protection to WT challenge, even under CD4+ T cell depletion, an immunodeficient condition commonly associated with cryptococcosis." (PMID 34568097, 2021). "Secondly, the study only assessed ART-naïve patients, whereas patients failing ART may also have CD4 cell counts < 100 cell/mm3 and become at risk of cryptococcal infection." (PMID 32832407, 2020). "Moreover, being male, living in rural areas, low CD4 count, and being hospitalized were statistically associated with cryptococcal infection." (PMID 30277315, 2019). "Given the clinical significance of CD4+ T cell deficiency to the susceptibility to cryptococcosis in patients, it is critical to know whether host protection can be established following HK-fbp1 vaccination in CD4+ T cell-deficient hosts." (PMID 31772051, 2019). "For instance, CD8+ T cells may compensate for the loss of CD4+ T cells to facilitate protection against cryptococcosis in an IFN-γ-dependent manner." (PMID 26500643, 2015). "It was associated with a low peripheral CD4 count, reflecting the importance of cell-mediated immunity in controlling cryptococcal infection, and with a poor inflammatory response at the site of infection, as evidenced by low CSF white cell counts and low levels of IFN-γ, TNF-α, and IL-6." (PMID 24319084, 2014). "As CD4+ T cells are required for GP-vaccine-mediated immunity, these findings raise the question of whether the immunocompromised populations most at risk for cryptococcosis could still benefit from the vaccine." (PMID 36732332, 2023). "Furthermore, immunocompetent hosts may also have unknown immunological perturbations such as idiopathic CD4+ T cell lymphocytopenia, anti-GM-CSF antibodies, or other genetic attributes that predispose them to cryptococcosis." (PMID 33808500, 2021). "In our study, the gradient of disease severity of patients is correlated with CD4+ T cell depletion, mirroring findings in HIV-associated cryptococcosis." (PMID 41245252, 2025). "Based on a comparative analysis of these 17 clinical cases, patients with disseminated cryptococcosis exhibited significantly lower CD4+ T cell counts than those with localized cryptococcal infections." (PMID 41245252, 2025). "CD4+ T cells are commonly classified into four subpopulations, namely Th1, Th2, Th17 and regulatory T cells, which play distinct roles in cryptococcal infection." (PMID 41017910, 2025). "Previously, HIV-associated cryptococcal infections have been a major concern, with an estimated global prevalence of cryptococcal antigenemia of 4.4% among HIV patients with CD4+ counts <200 cells/μL, corresponding to approximately 179,000 cases in 2020." (PMID 40672832, 2025). "We propose that in advanced HIV infection complicated by cryptococcosis—commonly characterized by CD4+ T cell depletion—complex immune phenotypes emerge." (PMID 40384976, 2025). "Such integrations address fundamental limitations in mortality data by incorporating HIV serostatus, CD4 counts, and antiviral treatment histories—critical for cryptococcosis surveillance." (PMID 41295569, 2025). "In total, about 90% of cryptococcal infections in individuals with HIV occur in those whose CD4 T cell counts are below 100 cells/mm3." (PMID 41375872, 2025).
cryptococcosis (continued). "In high prevalence regions, current recommendations are to screen individuals with blood CD4+ T cell counts less than 200 cells/μl for serum cryptococcal antigen (CrAg) and then preemptively treat those who test positive for presumed cryptococcosis." (PMID 40198673, 2025). "Defective cellular immunity is a major risk factor for progressive and/or disseminated cryptococcal infection and is most commonly observed with HIV infection and other immunosuppressive conditions that impair the number and/or function of CD4+ T lymphocytes." (PMID 38921420, 2024). "This approach is different from the advice for cryptococcosis, where patients with a low CD4 count are advised to be screened for the presence of cryptococcal antigen, to allow antifungal treatment in order to prevent IRIS after starting ARV." (PMID 38941354, 2024). "CAF01-adjunvanted subunit vaccines induce improved fungal control and augmented CD4+ T cell recruitment following cryptococcal infection." (PMID 38712080, 2024). "Numerous studies have underscored the pivotal role of CD4+ T cells in the immune response against cryptococcal infections, highlighting their significance in both controlling the infection and in vaccine-mediated protection." (PMID 38712080, 2024). "In humans and experimental mouse models, CD4+ T-cell immunity is required for protection against cryptococcosis." (PMID 38980038, 2024). "Here, we demonstrate that Batf3 cDC1s are important drivers of protective Th1 CD4 T-cell responses required for clearance of cryptococcal infection." (PMID 38349130, 2024). "Investigations have highlighted the critical function of CD4+ T cell-mediated Th1 immune responses in forestalling cryptococcosis within animal models." (PMID 38774865, 2024). "Recent studies have suggested that routine screening of HIV-infected patients with a CD4+ T-cell count <100 cells/μl for cryptococcal infection can prevent CM in both resource-limited and high-income countries." (PMID 37251371, 2023). "Monitoring the CD4+ T-cell count in peripheral blood is a convenient and reliable method to predict the severity and clinical outcomes of patients with cryptococcosis." (PMID 37251371, 2023). "Vaccination with a genetically modified yeast strain of C. neoformans, known as H99γ, which produces IFN-γ, has been shown to induce protective immunity against cryptococcosis in mice that lack CD4+ T cells." (PMID 37367569, 2023). "CD8+ T cells also produce TNF-α and Th1 cytokines during cryptococcal infections, whereas CD4+ T cells secrete only Th2 cytokines." (PMID 37251371, 2023). "Accordingly, 9% of infected HIV participants in two cohorts diagnosed in the first episode of cryptococcosis presented CD4 ≥ 100 cells/μL." (PMID 36547617, 2022). "The vast majority of patients with cryptococcosis have qualitative or quantitative defects in CD4+ T cell function." (PMID 35089095, 2022). "In 2017, an update of global cryptococcosis estimated that there were 278,000 people positive for cryptococcal antigen in people with <100 CD4/mm3." (PMID 35889106, 2022). "CD4+ T cells are the most critical component of the adaptive protective immune response to naturally acquired cryptococcal infection." (PMID 35089095, 2022). "CrAg prevalence was 4.3% and 4.9% in those with ≤200 and ≤100 CD4 cells/μL, respectively, similar to previous estimates of prevalence of cryptococcosis among PLHIV in sub‐Saharan Africa (SSA)." (PMID 34347366, 2021). "The adoption of routine screening for cryptococcal infection among patients with a CD4 cell count below 100 cells/μl and pre-emptive therapy for cryptococcal meningitis will result in reduction of CM associated morbidity and mortality." (PMID 32853215, 2020). "The CD4 T cells and innate mechanisms are important in control of lung infection while a combination of factors is required to control systemic cryptococcosis." (PMID 31871098, 2020).